RN7SL620P (RNA, 7SL, cytoplasmic 620, pseudogene)
Gene: Miscellaneous RNA gene on chromosome 17 (16,710,059 to 16,710,361, forward strand). Ensembl gene ENSG00000276088.
Homologues: Orthologues: chimpanzee Metazoa_SRP (98% identical). Paralogues in human: Metazoa_SRP (99% identical), RN7SL627P (99% identical), Metazoa_SRP (98% identical), RN7SL1 (84% identical), RN7SL2 (83% identical), RN7SL3 (83% identical), RN7SL786P (81% identical), RN7SL492P (81% identical), RN7SL679P (81% identical), RN7SL828P (80% identical), RN7SL664P (80% identical), RN7SL714P (80% identical), and 702 more.